IL6 (interleukin 6)
Diseases named in the same sentence as IL6 in open-access papers (continued):
Sharing a sentence is not in itself a finding about the gene and the disease.
cholesteatoma (9 papers, 2016 to 2023). A pathologic process characterized by the proliferation of keratinizing squamous epithelium resulting in the accumulation of keratin and cells in the middle ear and/or mastoid. "High levels of IL-6 in patients with cholesteatoma are associated with the injury degree of the ossicle and the poor prognosis of the disease." (PMID 37998605, 2023). "Cholesteatoma is caused by chronic inflammation of the middle ear, and human cholesteatoma tissue secretes proinflammatory cytokines, such as IL-1β, IL-6, TNF-α, and PGE24,21." (PMID 37537159, 2023). "Firstly, although several past studies on cholesteatoma explored not only MMP2 but also IL-6, other MMPs, TREM-2, and EGFR, this study focused only on the expression of MMP2 mRNA." (PMID 33778077, 2021). "NF-κB target genes particularly include pro-inflammatory cytokines like TNFα, IL-1α, IL-1ß, IL-6, and IL-8 and were shown to be upregulated in cholesteatoma tissue." (PMID 31947538, 2020). "Bone resorption and destruction was also shown to be positively correlated to inflammation, the presence of bacterial lipopolysaccharides (LPS), and expression of inflammatory mediators like TNFα, IL-1α, and IL-6 in cholesteatoma." (PMID 31947538, 2020). "The results of our studies on the ex vivo model were correlated with the results obtained from in vitro studies, in which we demonstrated the impact of sEVs from cholesteatoma patients on the functions of epithelial cells and the production of the pro-inflammatory cytokine IL-6." (PMID 37998605, 2023). "In comparison to sEVs isolated from the plasma of controls, cholesteatoma-derived sEVs significantly enhanced keratinocyte proliferation and IL-6 production (p < 0.05), potentially by engaging multiple activation pathways including MAPKp44/p42, STAT3, and the NF-κB pathway." (PMID 37998605, 2023). "In this study, levels of IL-6 were elevated after stimulation with cholesteatoma-derived sEVs." (PMID 37998605, 2023). "In detail the expression of the cytokines, e.g. IL-1α IL-1β and IL-6, TNF-α, GM-CSF and the chemokine IL-8, is elevated in cholesteatoma." (PMID 33627146, 2021). "In human acquired cholesteatoma, the expression of proinflammatory cytokines (IL-1β, TNF-α and IL-6) and matrix metalloproteinases (MMP-2, MMP-8 and MMP-9) were up-regulated, and their expression levels were positively correlated with TREM-2 expression." (PMID 27934908, 2016). "First, in human acquired cholesteatoma, bacterial infection induces high TREM-2 expression on the surface of DCs, which results in abundant IL-β and IL-6 secretion and amplifies the inflammatory response." (PMID 27934908, 2016). "Upon LPS challenge, we could detect a significantly higher expression of IL-1α, IL-1β, IL-6 and IL-8 in stem cells and of TNF-a, GM-CSF and CXCL-5 in stem cells and fibroblasts derived from cholesteatoma." (PMID 33627146, 2021). "Moreover, many of these cytokines promote peri-matrix angiogenesis (EGF, PDGF, IL-8, TGFα) and osteoclastogenesis/bone resorption (IL-1, IL-6, PTHrP, receptor activator of nuclear factor kappa-B ligand (RANKL), which are both responsible for cholesteatoma proliferation and local aggressiveness." (PMID 37623440, 2023). "Hence the presence of inflammatory mediators in cholesteatoma tissue was studied and exhibits a higher presence of the cytokines TNFα, IL-6, IL-8, IL-1α, and IL-1ß in comparison to non-inflamed external auditory canal skin tissue." (PMID 31947538, 2020). "Therefore, it could be inferred that TREM-2 might amplify the inflammatory response in human acquired cholesteatoma and then increase the proinflammatory cytokines levels (IL-1β, TNF-α, and IL-6) while promoting MMP secretion." (PMID 27934908, 2016).
chronic bronchitis (9 papers, 2014 to 2024). A type of chronic obstructive pulmonary disease characterized by chronic inflammation in the bronchial tree that results in edema, mucus production, obstruction, and reduced airflow to and from the lung alveoli. "Adipsin, lipocalin-2, IL-6 and resistin were significantly higher in the group with chronic bronchitis." (PMID 36291711, 2022). "The extent of neutrophil accumulation in the lung appears to correlate with circulating IL-6 levels and be more marked in those with a chronic bronchitis phenotype." (PMID 30674586, 2019). "In this context, our results revealed that the effectiveness of the model to induce chronic bronchitis is mainly characterized by increased number of neutrophils and lymphocytes in BAL, followed by increased levels of proinflammatory cytokines (IL-1β, IL-6, CXCL1, IL-17, and TNF-α)." (PMID 29326759, 2017). "In a similar animal study the increased levels of IL6, IL8 and LPO (lipoperoxide) in smokers with chronic bronchitis is compared with non-smokers." (PMID 25031491, 2014).
Cryptococcal meningitis (9 papers, 2015 to 2022). Meningeal inflammation produced by cryptococcus neoformans, an encapsulated yeast that tends to infect individuals with acquired immunodeficiency syndrome and other immunocompromised states. "IL-6 has been reported as a potential biomarker of IRIS associated with MAC and cryptococcal meningitis (CM)." (PMID 34198803, 2021). "Moreover, lenalidomide induces a sustained decrease in plasma IL-6, TNF-α, CRP, D-dimer, and CA-HIV-1 RNA from PBMCs in patients with HIV-associated cryptococcal meningitis." (PMID 35967862, 2022). "For example, the HIV-infected individuals who were treated for cryptococcal meningitis and survived, had higher levels of several immune modulators in the CSF (IFNγ, TNF-α, IL-6 and IL-8) compared to those who did not." (PMID 29970809, 2018).
Duchenne muscular dystrophy (9 papers, 2012 to 2025). Duchenne muscular dystrophy (DMD) is a neuromuscular disease characterized by rapidly progressive muscle weakness and wasting due to degeneration of skeletal, smooth and cardiac muscle. "Accordingly, the correlation between FAPs and IL-6 was also highlighted in the murine model of Duchenne muscular dystrophy (mdx mouse), a genetic muscle disease characterized by the progressive degeneration of muscle tissue, by inefficient regeneration, and by fibrotic/fatty tissue deposition." (PMID 30862132, 2019). "IL6 has been shown to play a role in Duchenne muscular dystrophy (DMD), one of the most common types of MD." (PMID 30072615, 2018). "In the mouse model (mdx) of Duchenne Muscular Dystrophy, IL-6 and muscle inflammation are elevated, which is believed to contribute to the chronic inflammation and failure of muscle regeneration in DMD." (PMID 22716658, 2012). "In Duchenne muscular dystrophy, the BMP4/SMAD8 pathway is upregulated alongside IL-6, a key inflammatory mediator." (PMID 40076910, 2025). "It is of interest to note that patients affected by Duchenne muscular dystrophy (DMD) showed low bone mineral density (BMD) Z-scores and high bone resorption marker and serum IL-6." (PMID 32479501, 2020).
familial Mediterranean fever (9 papers, 2014 to 2023). Familial Mediterranean fever (FMF) is an autoinflammatory disorder characterized by recurrent short episodes of fever and serositis resulting in pain in the abdomen, chest, joints and muscles. "Studies of autoinflammatory diseases, such as familial Mediterranean fever, cryopyrin-associated periodic syndrome, and tumor necrosis factor receptor-associated periodic syndrome, have shown IL-6 to be a promising therapeutic target." (PMID 35958618, 2022). "Hyper-activation of the pyrin inflammasome by MEFV-activating mutations causes Familial Mediterranean fever (FMF), a disease that is characterized by high levels of IL-1β, IL-6, IL-8, and IL-12, recurring fever episodes, arthritis, and low bone mass." (PMID 31520179, 2019). "A clinical case report found that inhibition of IL-6 expression could relieve familial Mediterranean fever." (PMID 31143120, 2019). "A functional link between IL-1β and IL-6 is also suggested by the observation that patients with familial Mediterranean fever (FMF), an auto-inflammatory disease, were successfully treated with TCZ." (PMID 25271853, 2014). "In familial Mediterranean fever (FMF), ex vivo LPS-stimulated PBMCs and monocytes produce more IL-1α and β, IL-6, IL-8, IL-12, IL-18, and TNFα, and in non-stimulated PBMCs higher production of IL-6 and TNFα was found, and also expression of CD11b was increased." (PMID 29515591, 2018).
folate deficiency (9 papers, 2019 to 2025). A nutritional condition produced by a deficiency of FOLIC ACID in the diet. "Folate deficiency also increased IL-6, TNF-α, and MCP-1 secretions of RAW 264.7 macrophage cell line, and enhanced intestinal inflammation due to decreased colonic regulatory T (Treg) cells in mice fed a folate-deficient diet." (PMID 37630806, 2023). "In conclusion, this study found that in the context of ischemia‐reperfusion, folic acid deficiency may trigger astrocytes' inflammatory response via the IL‐6/JAK‐1/pSTAT3 pathway." (PMID 36794521, 2023). "Furthermore, folate deficiency is directly related to increased levels of inflammatory markers such as IL-β, IL-6, and TNF-α." (PMID 35565885, 2022). "Higher MCP-1 and IL-6 levels in folate-deficient 3T3-L1 cells suggested that adipocytes hypertrophy and inflammation might contribute to promoted diet-induced adiposity by folate deficiency." (PMID 35548560, 2022). "In mice, dietary folic acid intake attenuated inflammation and fibrosis in MASH, and macrophage expression of IL-6 and TNF-α was increased with folate deficiency." (PMID 39842721, 2025). "Folate deficiency may exert pro-inflammatory signaling by enhancing the monocyte–macrophage system, and the production of the inflammatory mediators, IL1β, IL6, TNFα, and MCP1, and monocytes were significantly increased when folate deficiency." (PMID 40740648, 2025). "Folate deficiency has been associated with impaired immune cell function and increased levels of tumor necrosis factor-alpha (TNF-α) and interleukin-6 (IL-6), which can contribute to impaired immunity, chronic inflammation, and the development of inflammatory diseases." (PMID 37960352, 2023). "Both HFF diet and folate deficiency increased renal MCP-1 and IL-6 contents, as well as TNF-α." (PMID 37630806, 2023). "It has been reported that folate deficiency might enhance the expression of the inflammatory mediators including IL-1β, IL-6 and TNF-α, independent of the concentration of homocysteine." (PMID 31296192, 2019).
hemorrhagic fever (9 papers, 2011 to 2024). An infectious disease caused by certain viruses or bacteria that can damage the walls of tiny blood vessels, making them leak, and can hamper the blood's ability to clot and cause severe, life-threatening illness. "Although reports of elevated IL-6 levels in the early acute phase in bleeding patients were published, others observed significantly higher IL-6 levels associated with hemorrhagic fever only in patients infected with DENV-2, but not with DENV-1." (PMID 39457019, 2024). "It is noteworthy that elevated levels of IL-6, IL-8, IL-10, G-CSF, and TNF-alpha, which were observed in MACV-infected STAT-1 knockout mice, are correlated with the severity of human Argentinean hemorrhagic fever, caused by the related Junín virus." (PMID 21672221, 2011). "However, pathological cytokine responses including IFNγ, IL-6, IL-10, TNFα, and IP-10, all of which are elevated in AB6 mice during fatal Ang71 infection, have been implicated in inducing vascular permeability with the onset of hemorrhagic fever after infection with the related Dengue virus (DENV)." (PMID 27463517, 2016). "In addition, we measured serum levels of vasoactive IL-6 and TNF-α proteins, which have been known to play an important role in inducing hemorrhagic fever and increasing vascular leakage." (PMID 34130738, 2021). "In addition, LASV subdues the cells of the immune system thus preventing their secretion of proinflammatory cytokines including tumor necrosis factor (TNF)-α, IL-6, and IL-8β, unlike the symptoms observed in other hemorrhagic fevers." (PMID 36680186, 2023).
Hyperbilirubinemia (9 papers, 2012 to 2025). An increased amount of bilirubin in the blood. "Increases in interleukin (IL)-6 and tumor necrosis factor-α, which are observed in the early stages of severe burns, have been reportedly associated with hyperbilirubinemia and organ dysfunction." (PMID 39895101, 2025). "Concentrations of IL-6 peaked at 1082 (95%CI: 914-1280) pg/mL in hyperbilirubinemia subjects compared to 890 (95%CI: 683-1160) pg/mL in the placebo group (over time both p<0.001, between groups p=0.1)." (PMID 37261364, 2023). "To investigate the effect of PGC-CDs on inflammatory factors of liver damage induced by hyperbilirubinemia, we tested the content of IL-6 and TNF-α." (PMID 36985691, 2023). "The results of this study suggested that PGC-CDs could inhibit levels of IL-6 and TNF-α in the treatment of hyperbilirubinemia and its associated liver damage, thereby reducing the mortality of hyperbilirubinemia." (PMID 36985691, 2023). "Cytokines e.g. interleukin-6 (IL6), tumor necrosis factors (TNF) are also been considered to depress excretory functions of the liver resulting in hyperbilirubinemia without rise in liver enzymes level." (PMID 33509122, 2021). "Absence of hyperbilirubinaemia and the inability of neutrophils to migrate into liver tissue in the septic PI3Kγ−/− mice were seen, notwithstanding higher levels of inflammatory cytokines (TNF-α and IL-6) and the chemoattractant MCP-1." (PMID 23152722, 2012).
intestinal cancer (9 papers, 2009 to 2025). "The expression of VEGF/VEGFR is associated with interleukin 6 (IL-6) signaling pathways in many cancers, such as breast and intestinal cancers." (PMID 27852059, 2016). "The possibility of metastatic breast, lung, or bowel cancers merits consideration in the establishment of differential diagnoses for a woman with suspicious ovarian mass and elevated IL-6." (PMID 36765633, 2023). "The possibility of metastatic breast, lung or bowel cancers merits consideration in the differential diagnosis for a woman with a suspicious ovarian mass and increased IL-6 concentration." (PMID 32042020, 2020). "Therefore, IL-6 is a crucial mediator of NAR's effect on intestinal cancer cell survival, which deserves further in-depth investigation." (PMID 40295196, 2025). "Previously, in a mouse model of intestinal cancer, sunitinib administration at a dosing protocol of 30 mg/kg every other day for 9 weeks resulted in a reduction in various inflammation-related factors, such as IL-6, IL-1α/1β, TNFα, and IFN-γ at the mRNA level within the GI tract." (PMID 38339116, 2024).
intestinal polyp (9 papers, 2017 to 2022). Discrete abnormal tissue masses that protrude into the lumen of the intestine. "The administration of a 2% curcumin diet decreased the total number of intestinal polyps by 75% and reduced IL-1β, IL-6 and TNF-α protein expression." (PMID 36547085, 2022). "The authors observed that treatment with EM was able to suppress the development of intestinal polyps and decreased the levels of IL-6 and cyclooxygenase-2." (PMID 35717620, 2022). "Other studies indicate that the level of IL-6 was 10-fold higher in the circulation and was increased by 89% in intestinal polyps in APCMin/+ mice at 26 weeks of age." (PMID 29707119, 2018). "IL-6 was observed mainly in the surface area of the cytoplasm of epithelial cells in intestinal polyps." (PMID 28584401, 2017). "In another experiment that we previously performed, IL-6 played an important role in the development of intestinal polyps in Min mice." (PMID 28420165, 2017). "Our results showed that acetazolamide reduced IL-6 levels in both the local intestinal polyps (i.e., the liver), and the entire mouse (i.e., the serum)." (PMID 28420165, 2017). "Moreover, erythromycin reduced the levels of interleukin-6 and cyclooxygenase-2 mRNA expression in intestinal polyps." (PMID 28584401, 2017). "IL-6 was observed mainly in the surface area of the cytoplasm of epithelial cells, and COX-2 was observed strongly in the stroma cells in the intestinal polyp of untreated Min mice." (PMID 28584401, 2017).
lower respiratory tract infections (9 papers, 2010 to 2025). "One of the most common side effects of targeting either the IL-6R (via Tocilizumab) or IL-6 (via Siltuximab) is increased risk of both upper and lower respiratory tract infections." (PMID 28953978, 2017). "Higher maternal plasma levels of IL-6 and CRP have also been associated with alterations in fetal growth and brain development, wheezing and lower respiratory tract infections, the incidence of which is increased in offspring of obese mothers." (PMID 30131724, 2018). "Therefore, the effect of lower respiratory tract infections on persistent reduction of IL-6 production capacities in circulatory monocytes via a long-term reprogramming of bone marrow myeloid progenitor cells certainly warrants further investigation." (PMID 34399830, 2021).
lung squamous cell carcinoma (9 papers, 2013 to 2026). "Radon exposure, IL-6 promoter variants, and lung squamous cell carcinoma in former uranium miners." (PMID 26372664, 2016). "In this study, we comprehensively evaluated the association between four IL6 promoter variants predicted by in silico analyses to affect binding of transcription factors and lung squamous cell carcinoma in former uranium miners with high levels of radon exposure." (PMID 26372664, 2016). "For IL6, high expression indicates a poor prognosis in lung squamous cell carcinoma (LUSC) and BLCA, while demonstrating protective effects for KIRC, illustrating the dual aspects of cancer progression." (PMID 39635438, 2024). "We present a female with squamous cell carcinoma of the lung that produced granulocyte colony-stimulating factor and interleukin-6." (PMID 23710188, 2013). "We encountered a case of lung squamous cell carcinoma that produced both G-CSF and IL-6." (PMID 23710188, 2013). "Here we present a case of lung squamous cell carcinoma that produced both G-CSF and IL-6." (PMID 23710188, 2013). "In lung squamous cell carcinoma, the low YTHDF1 group was also mainly enriched in immunity-related signaling pathways (allograft rejection, IL2-STAT5 signaling, inflammatory response, IL6-JAK-STAT3 signaling, and TNFA signaling via NFKB and interferon gamma response)." (PMID 36479088, 2022).
macular holes (9 papers, 2011 to 2025). A hole in the macula of the retina. "Vitreous IL-6 concentration also showed a similar trend in the case of control patients with macular holes." (PMID 22025890, 2011). "In this regard, we analyzed the concentration of vitreous proteins that were higher in the ED patients than in control patients with macular holes, and the absolute intravitreous concentration of IL-6 and VEGF were adjusted by the total vitreal protein." (PMID 22025890, 2011). "To compare, we also genotyped patients with macular holes, those representing the control group for vitreous analysis, and found that vitreous IL-6 levels but not VEGF levels significantly correlate with −174G/C polymorphism of the IL-6 gene." (PMID 22025890, 2011). "Aqueous flare values and the vitreous levels of VEGF, IL-6, MCP-1, sICAM-1, and sVEGFR-2 were compared between previously untreated patients with BRVO and patients with macular hole (MH)." (PMID 24884703, 2014). "At the proliferative stage of ED, significantly higher levels of vitreous IL-6 (p=<0.0001) and VEGF (p=<0.0001) were found compared with the vitreous of patients with macular holes." (PMID 22025890, 2011).